DNMT3B (DNA methyltransferase 3 beta)
Diseases named in the same sentence as DNMT3B in open-access papers (continued):
Sharing a sentence is not in itself a finding about the gene and the disease.
cervical cancer (14 papers, 2009 to 2025). A primary or metastatic malignant neoplasm involving the cervix. "RNA-Seq analysis revealed that overexpression of the HPV16/18 E6/E7 genes upregulated GP6, CD36, HDAC6, ESPL1, and DNMT3B among the differentially expressed genes (DEGs) associated with cervical cancer." (PMID 39411320, 2024). "Our results indicate that alteration in HDAC6 and DNMT3B expression is associated with high-risk human papillomavirus infection and could promote the occurrence and development of cervical cancer." (PMID 39411320, 2024). "In a similar manner, miR-29a downregulates DNMT3A and DNMT3B expression in HeLa and C-33A cervical cancer cells, which results in the demethylation and subsequent upregulation of p16." (PMID 41226543, 2025). "Further, qRT-PCR and Western blot analyses indicated that both HPV16/18 E7 can upregulate the expression of HDAC6 and DNMT3B, genes associated with HPV infection-related cervical cancer." (PMID 39411320, 2024). "Studies have found that DNMT3B mRNA transcripts are significantly overexpressed in the highly invasive cervical cancer cell lines HeLa and Caski." (PMID 39411320, 2024). "Some studies have found that DNMT3B mRNA transcripts are significantly overexpressed in the highly invasive cervical cancer cell lines HeLa and Caski." (PMID 39411320, 2024). "In particular, research has found significant overexpression of DNMT3B mRNA transcripts in cervical cancer cell lines Hela and Caski." (PMID 39411320, 2024). "To further investigate the regulatory effect of the E7 gene on HDAC6 and DNMT3B in HPV-negative cervical cancer cells, we infected C33A cells with recombinant viruses expressing the E7 gene (Ad4-HPV16E7, Ad4-HPV16E6E7, Ad4-HPV18E7, and Ad4-HPV18E6E7)." (PMID 39411320, 2024). "RPP25, BARD1, BRCA1, CD3EAP, CSTF2, DARS2 and DNMT3B was up-regulated in most of cervical cancer tissues compared with corresponding normal cervix tissues." (PMID 34863153, 2021). "Previous studies show that SFN decreased DNMT1, DNMT3A, and DNMT3B expression, leading to global DNA hypomethylation in human breast, prostate, and cervical cancer cell lines." (PMID 32878338, 2020). "We previously showed that DNMT3B is amplified in the cervical cancer cell line SiHa and found a correlation between increased DNMT3B gene copy numbers and elevated mRNA expression in 78% of CxSCCs." (PMID 19486517, 2009). "Furthermore, the recombinant viruses expressing HPV16/18 E7 can upregulate the HDAC6 and DNMT3B genes involved in cervical cancer pathways, thereby influencing the cell cycle." (PMID 39411320, 2024). "Therefore, we collected a set of genes related to cervical cancer-associated pathways and used the ssGSEA algorithm to calculate the scores of the HDAC6 and DNMT3B genes in these pathways." (PMID 39411320, 2024). "Therefore, we assembled a set of genes associated with these cervical cancer-related pathways and employed the ssGSEA algorithm to calculate the scores of the HDAC6 and DNMT3B genes in these pathways." (PMID 39411320, 2024). "Similarly, other methytransferase family members, such as DNMT3B, are involved in invasive cervical cancer cells as well as DNMT3B-mediated silencing of the protein tyrosine phosphatase receptor type R." (PMID 31426393, 2019). "On the other hand, knockdown of DNMT1 and DNMT3B reduces methylation of the SORBS3-β promoter, thereby increasing its expression in SiHa cervical cancer cells." (PMID 41226543, 2025). "Through cross-screening of HPV infection-related DEGs and cervical cancer-related DEGs, we identified five significantly upregulated DEGs, e.g., GP6, CD36, HDAC6, ESPL1, and DNMT3B." (PMID 39411320, 2024). "In cervical cancer, DNMT3A and DNMT3B regulated the methylation of p16 promoter, and affected its expression." (PMID 39284825, 2024). "Epigenetic silencing of PTPRR resulting from DNMT3B-mediated methylation activates MAPK signaling, promotes metastasis and serves as a biomarker of invasive cervical cancer." (PMID 37965307, 2023).
cervical cancer (continued). "In the cervical cancer (HELA) cell line, EGCG (25 μM) suppressed DNMT3B activity and expression, leading to promoter hypomethylation and the reactivation of RARβ, CDH1, and DAPK1." (PMID 32878338, 2020). "Currently, functions and mechanisms of DNMTs in cervical cancer cells remained unclear, and whether DNMT1 and DNMT3b act synergistically or through other ways exploration efforts were still required study." (PMID 21999220, 2011). "DNMT1 silencing in cervical cancer cells could induce re-expression of most tumor suppressor genes by demethylating its promoter region, and co-silencing of DNMT1 and DNMT3b might perform a greater inhibitory effect on tumorigenesis." (PMID 21999220, 2011).
breast tumors (12 papers, 2004 to 2025). "Simultaneous analysis of RNA-seq transcriptomic and methylomic data from the TCGA–BRCA dataset reveals that the aberrant activation of DNMT3B in breast tumours induces a significant increase in promoter methylation for 1939 genes." (PMID 40585280, 2025). "Previous study indicated that DNMT1, DNMT3A, and DNMT3B are upregulated in breast tumor tissues compared with normal breast tissues." (PMID 36982660, 2023). "The difference in DNMT3b expression between the high β and low β groups of breast tumors became far more modest when the mRNA expression levels were normalized according to those of the cell proliferation marker PCNA (P = 0.060)." (PMID 20830311, 2010). "We observed increased mRNA expression levels of DNMT3b in the high β group of breast tumors (P = 0.034), with a mean expression level of 5.76 in the low β tumor group and 6.52 in the high β tumor group." (PMID 20830311, 2010). "Besides, we performed IHC staining of DNMT3B on a tissue microarray (TMA) of 140 human breast tumor specimens." (PMID 37881785, 2023). "One study analyzed the association between multiple miRNAs expression and DNMT3B-induced DNA hypermethylation, and concluded that dysregulation of miRNAs led to aberrant DNA hypermethylation via suppressing post-transcriptional level of DNMT3B in basal-like breast tumor." (PMID 35620052, 2022). "Breast tumors displaying a CIMP also showed increased expression of DNMT3b." (PMID 20830311, 2010). "Tumor cells exhibiting DNMT3b overexpression are likely to exhibit methylation-based aberrant gene expression; one study showed that breast tumors that overexpress DNMT3b are more likely to be ESR1-negative, display increased proliferation, and be associated with poor patient prognosis." (PMID 18221536, 2008). "Moreover, these breast tumors showed increased DNMT3b mRNA levels." (PMID 20830311, 2010). "Thus, it seems reasonable to expect that aberrant expression of DNMT3b protein may produce significant differences in tumor biology for breast tumors of the hypermethylator phenotype." (PMID 18221536, 2008). "Elevated expression of DNA methyltransferases (DNMTs), mainly DNMT1 and DNMT3B, has been reported to be largely responsible for the aberrant WIF1 hypermethylation in breast tumors." (PMID 25918249, 2015). "Since overexpression of DNMT is thought to be an early event in carcinogenesis, elevated DNMT3b protein (which characterizes the hypermethylator phenotype in vitro) may constitute an important biomarker for early detection in patients developing breast tumors of the hypermethylator phenotype." (PMID 18221536, 2008). "Moreover, high expression levels of DNMT3B and CTCF are critical in the epigenetic inactivation of BRCA1 in sporadic breast tumors." (PMID 28127428, 2017). "To investigate whether the difference in methylation profiles between breast tumors is related to differences in the DNA methyltransferase (DNMT) machinery, we compared the expression levels of DNMT1, DNMT3a and DNMT3b mRNAs between the high β and low β groups of breast tumors." (PMID 20830311, 2010).
endometriosis (11 papers, 2012 to 2025). The growth of functional endometrial tissue in anatomic sites outside the uterine body. "In addition to interaction with methylating enzymes, interaction with demethylating enzymes, such as DNA methyltransferases (DNMT3B), may be the cause of abnormal expression of SF-1 in endometriosis." (PMID 32370117, 2020). "Specifically, selective DNMT3B inhibitors have been proposed as potential therapeutic targets for endometriosis treatment." (PMID 40072055, 2025). "While further investigation in the context of endometriosis is needed, structure-based drug design approaches targeting DNMT3B have already identified promising compounds for cancer therapy, suggesting potential applications for other epigenetic disorders." (PMID 40072055, 2025). "In patients with endometriosis, DNMT1, DNMT3A, and DNMT3B are overexpressed in the epithelial component of endometriotic implants compared to normal controls or the eutopic endometrium of women with endometriosis." (PMID 40951281, 2025). "Scientists have also proven that the expression of one of the DNA methyltransferases (DNMT3B) is visibly changed in stromal cells in endometriosis patients." (PMID 35409163, 2022). "The DNMT1, DNMT3A, and DNMT3B expression levels were reported to be elevated in ectopic endometria compared to normal controls or in the eutopic endometrium of women with endometriosis." (PMID 32370117, 2020). "DNMT1, DNMT3A and DNMT3B transcripts in eutopic mid-luteal endometrium from infertile women with endometriosis, fertile women and infertile women with tubal occlusion." (PMID 22233680, 2012). "DNMT3B binds to promoter regions of essential genes in the pathogenesis of endometriosis." (PMID 35409163, 2022). "Thus, differentiated DNMT3B expression and binding to critical gene promoters in endometriotic stromal cells may contribute to aberrant DNA methylation that misdirects gene expression in endometriosis and contributes to altered response of these cells to steroid hormones." (PMID 32370117, 2020). "Many studies reported the up-regulated expression of only for the DNMT3A and not for DNMT1 and DNMT3B in the endometriotic tissue which leads to hypermethylation in endometriosis." (PMID 32042366, 2020).
oral cancer (11 papers, 2014 to 2023). "In addition, the up-regulation of DNMT3B was significantly linked to the risk of lymph node involvement, recurrence of the disease and shorter survival period in patients in advanced stage of oral cancer." (PMID 33369458, 2020). "When oral cancer cells with control vectors and those with DNMT3b silencing vectors were subcutaneously implanted into mice, we found that the growth inhibiting effect induced by DNMT3b silencing vector associated with lower expression levels of EMT- and angiogenesis-related factor." (PMID 24625449, 2014). "Therefore, it was determined whether this was the mechanism underlying the effects of DNMT3b on oral cancer invasiveness." (PMID 24625449, 2014). "As reported by several studies, DNMT3B was found to be the most commonly studied gene in relation to oral cancer." (PMID 33369458, 2020). "From our microarray data, we also found that DNMT1, DNMT3A and DNMT3B were overexpression in oral cancer." (PMID 32238162, 2020). "Alterations in the EGFR gene copy number, or alterations in miR-7, miR-21, mRNA-KIFGA, OPN, DEPDC1B, EZH2, deltaNp63, and DNMT3B were significant for early evaluation and correlation with oral cancer." (PMID 31019584, 2019). "In the present data, knockdown of DNMT1 or DNMT3B restored the expression of TIMP3 in the oral cancer cell lines." (PMID 31624299, 2019). "The predictive powers of DNMT3b were further examined in terms of the clinical outcome of oral cancer." (PMID 24625449, 2014). "We therefore outlined the main signaling pathways that are thought to link IL-6 and DNMT3b to oral cancer." (PMID 24625449, 2014). "Using multivariate analysis, expression of DNMT3b and disease recurrence was significant predictors for overall survival in the 125 oral cancer patients." (PMID 24625449, 2014). "By the experiments in which IL-6 signaling was suppressed by IL-6 antibody, we found that activated IL-6 signaling plays an important role in DNMT3b activation associated with activated STAT3 and PI3K in oral cancer cells." (PMID 24625449, 2014). "The DNMT3b silencing vector induced oral cancer cells to increase their epithelial characteristics as determined by changes in expression of E-cadherin, a hallmark of EMT and vimentin." (PMID 24625449, 2014). "The activation of inflammatory marker IL-6 could be the vital signal responsible for the induction and over-expression of DNMT3B in oral cancer." (PMID 33369458, 2020). "Furthermore, in vitro data showed that DNMTs were increased in oral cancer cell lines, except DNMT3B for Ca9-22 and Cal-27 cell lines." (PMID 31624299, 2019). "This study was the first to demonstrate that betel nut alkaloid may recruit DNMT3B to regulate miR-486-3p/DDR1 axis in oral cancer andmiR-486-3p and DDR1 may serve as potential therapeutic targets of oral cancer." (PMID 31253192, 2019). "In conclusion, IL-6 –DNMT3b axis could be used to predict the prognosis of oral cancer in clinics, and targeting DNMT3b could represent a promising treatment strategy." (PMID 24625449, 2014). "Activated IL-6 signaling might be responsible to the induction of DNMT3b overexpression on oral cancer." (PMID 24625449, 2014). "The role of DNMT3b and its predictive power in the prognosis of oral cancer were identified." (PMID 24625449, 2014). "Furthermore, expression of DNMT3b was significantly linked with the risk of lymph node involvement, disease recurrence and shorter survival in patients with pathological stage III-IV oral cancer." (PMID 24625449, 2014). "Furthermore, 125 oral cancer tissue specimens were analyzed using immunohistochemical staining on tissue microarray slides, and correlations calculated between the level of DNMT3b and the clinical outcome of patients." (PMID 24625449, 2014). "The findings highlight the contribution of DNMT3b staining to poor prognosis in oral cancer." (PMID 24625449, 2014). "The findings suggest that DNMT3b staining might have the predictive value in the prognosis of oral cancer." (PMID 24625449, 2014).
oral cancer (continued). "Taken together, these findings demonstrated that arecoline or NNK exposure could downregulate the miR-30a and miR-379 in oral cancer cells, consequently increase the DNMT3B protein level and recruit DNMT3B binding to ADHFE1 and ALDH1A2 promoter and caused DNA methylation." (PMID 32238162, 2020). "Hence, the researchers suggest that DNMT3B could be used as a promising therapeutic target for oral cancer." (PMID 33369458, 2020). "Therefore, it is suggested that activation of IL-6 signaling might be responsible to the increased DNMT3b in oral cancers." (PMID 24625449, 2014). "There was a positive link between DNMT3b staining and LN metastasis and disease failure in patients with oral cancer.As demonstrated using migration scratch and invasion assays, DNMT3b silencing vectors attenuated the invasion capacity of oral cancer cells in vitro." (PMID 24625449, 2014). "Of the 125 oral cancer tissues assayed for DNMT3b and DNMT1 using IHC analysis, 76 (61%) gave DNMT3b positive immunoreactivity but only 36% (45/125) with DNMT1 positive staining." (PMID 24625449, 2014). "The DNMT3b silencing vectors induced an increase in E-cadherin and decreases in VEGF and MMP-9 in oral cancer cells." (PMID 24625449, 2014). "In this study, we found that NNK and arecoline treatment could recruit DNMT3B to ADHFE1 and ALDH1A2 promoter region, subsequently repressed the expression of ADHFE1 and ALDH1A2 in oral cancer." (PMID 32238162, 2020). "In this study, we found that arecoline treatment could recruit DNMT3B to ANK1 promoter and suppresses ANK1 and miR-486-3p expression, subsequently upregulated expression of DDR1 in oral cancer." (PMID 31253192, 2019). "The data obtained from the present study revealed that the increased DNMT3b induced by IL-6, which might be mediated by the activation of STAT3 and PI3K signaling, is critical in tumor aggressiveness and prognosis of oral cancer." (PMID 24625449, 2014). "To further investigate whether DNMT3b was responsible for aggressive tumor growth of OSCC, we suppressed DNMT3b in oral cancer cells using a silencing vector." (PMID 24625449, 2014). "Regarding clinical data, the incidence of DNMT3b immunoreactivity in oral cancer specimens was significantly higher than in non-malignant epithelium, and positively linked to expression of IL-6." (PMID 24625449, 2014).